DEFB104B (defensin beta 104B)
Description:
Has antimicrobial activity. Synergistic effects with lysozyme and DEFB103.
Synonyms: BD-4; DEFB-4; hBD-4
Gene: Protein-coding gene on chromosome 8 (7,470,308 to 7,475,082, reverse strand). Ensembl gene ENSG00000177023.
Subcellular location: Secreted
Pathways (Reactome):
Immune System: Beta defensins; Defensins
Gene Ontology:
Molecular function: chemoattractant activity
Biological process: cellular response to phorbol 13-acetate 12-myristate; defense response to Gram-negative bacterium; defense response to Gram-positive bacterium; innate immune response; monocyte chemotaxis; positive chemotaxis
Cellular component: extracellular region
Homologues: Orthologues: chimpanzee DEFB104 (100% identical), mouse Defb22 (18% identical), rat Defb22 (17% identical). Paralogues in human: DEFB104A (100% identical), DEFB116 (31% identical), DEFB108B (29% identical), DEFB115 (29% identical), DEFB129 (28% identical), DEFB108C (26% identical), DEFB118 (26% identical), DEFB121 (26% identical), DEFB127 (26% identical), DEFB123 (24% identical), DEFB135 (24% identical), DEFB119 (22% identical), and 7 more.